EGFR (epidermal growth factor receptor)
Diseases named in the same sentence as EGFR in open-access papers (continued):
Sharing a sentence is not in itself a finding about the gene and the disease.
colorectal cancer (continued). "EGFR activation has been implicated in the development of many solid tumors, such as colorectal cancer and pancreatic ductal adenocarcinoma." (PMID 39123483, 2024). "Increased expression of PSEN1 in colorectal cancer is associated with enhanced tumor development through heightened EGFR signaling via NOTCH1 processing and activation of the COX-2-PGE2 pathway." (PMID 39267750, 2024). "EGFR-directed therapy with agents like cetuximab and panitumumab is a cornerstone in treating colorectal cancers with a wild-type EGFR status, as mutations in the EGFR pathway, such as RAS mutations, can negate the benefits of such treatments." (PMID 39199633, 2024). "Treatment approaches discovered driver events in colorectal cancer, such as mutations in EGFR, led to profound improvements in clinical outcomes." (PMID 39192986, 2024). "Although EGFR‐amplified colorectal cancer is also rare (1%), it has been reported to be associated with a good prognosis because of the benefits of anti‐EGFR antibodies." (PMID 39540676, 2024). "Although previous studies investigating the association between GWMS and the efficacy of anti-EGFR antibodies have focused on Japanese patients, the present study was performed on Western patients with colorectal cancer." (PMID 38862615, 2024). "Although less frequent than KRAS mutations, neuroblastoma ras viral oncogene homolog (NRAS) mutations occur in 5–9% of colorectal cancer cases, typically associated with tumor progression and resistance to anti-EGFR therapies in KRAS wild-type tumors." (PMID 39684219, 2024). "Mutations and overexpression of proteins such as EGFR (epidermal growth factor receptor) are associated with various types of cancers, including lung and colorectal cancers." (PMID 39685591, 2024). "Some studies have found that colorectal cancer patients with PIK3CA gene mutations have poor efficacy when using anti-EGFR monoclonal antibodies, with significantly shortened progression-free survival and overall survival." (PMID 39555098, 2024). "The overexpression of EGFR in colorectal cancer is associated with an advanced stage of colorectal cancer." (PMID 38542291, 2024). "PRSS1 encodes pancreatic serine proteinase, trypsin-1 whose expression has been associated with the sensitivity to EGFR inhibitors of cetuximab in colorectal cancers, and its inhibition reduces the tumor growth." (PMID 39160568, 2024). "The analysis focused on only three genetic mutations (KRAS, BRAF, EGFR), despite colorectal cancer’s complexity with many potential driver mutations." (PMID 39722096, 2024). "KRAS G12V/G12D/G12S/G13D mutations were suggested to confer resistance to anti-EGFR antibody therapies in colorectal cancer patients." (PMID 37511664, 2023). "Colorectal cancers with RAS mutations are resistant to epidermal growth factor receptor (EGFR) antibodies." (PMID 37604687, 2023). "RAS somatic variants are predictors of resistance to anti-EGFR therapy for colorectal cancer (CRC) and affect the outcome of the disease." (PMID 37628934, 2023). "For example, an increased abundance of let-7 miRNA has been associated with a positive response to anti-epidermal growth factor receptor (EGFR) therapy in colorectal cancer (CRC) patients." (PMID 37514018, 2023). "The rapid feedback activation through EGFR pathways caused by BRAF inhibition in colorectal cancer was subsequently overcome by the addition of anti-EGFR agents, resulting in significant improvements to OS and ORR." (PMID 37124503, 2023).
colorectal cancer (continued). "In colorectal cancer patients, the incidence in Western countries of EGFR mutation was 0.34%, while it was 12% in Japan and 22.4% in South Korea." (PMID 37296986, 2023). "It is well established that this limited activity of BRAF inhibitor monotherapy in BRAF-mutant colorectal cancer is associated with activation of epidermal growth factor receptor (EGFR)-mediated signaling." (PMID 36045401, 2022). "The cell signaling factors EGFR, EphA2, and Ephexin1 are associated with lung and colorectal cancer and play an important role in tumorigenesis." (PMID 35668076, 2022). "The ultimate goal is to discover new therapeutic opportunities beyond the currently available BRAF inhibitors, which are currently the only approved drugs, in combination with anti-EGFR therapies, for colorectal cancers with V600E mutations." (PMID 36295658, 2022). "Approximately 50% of patients with colorectal cancer have mutations in the epidermoid growth factor receptor (HER1, EGFR, or Erbb1) gene." (PMID 36005935, 2022). "An over-expression of the epidermal growth factor receptor (EGFR) has been observed in colorectal cancer and is associated with aggressive disease and poor prognosis." (PMID 36307775, 2022). "Preclinical models of BRAFV600E mutated colorectal cancer have shown that BRAF inhibition causes rapid feedback activation through the epidermal growth factor receptor (EGFR)." (PMID 35492830, 2022). "EGFR overexpression has been found in 50–80% patients of colorectal cancer (CRC) and its increased levels are associated with aggressive disease and poor prognosis." (PMID 36307775, 2022). "JMT-101 is an anti-EGFR mAb which has shown favorable a toxicity profile in patients with colorectal cancer and is being assessed in combination with afatinib or osimertinib in a phase Ib trial in patients with EGFR exon 20 insertion mutations (NCT04448379)." (PMID 34913823, 2022). "From 157 patients with lung or colorectal cancer, 29 patients (18%) showed positive ctDNA liquid biopsies, with genetic mutations in EGFR (n = 9), BRAF (n = 3), neuroblastoma rat sarcoma virus (NRAS) (n = 1), and Kirsten rat sarcoma virus (KRAS) (n = 16)." (PMID 36497340, 2022). "This genetic alteration is detected in approximately 40% of colorectal cancers and is linked with resistance to anti-epidermal growth factor receptor therapy." (PMID 36291953, 2022). "EGFR Q787Q polymorphism is a poor prognostic factor for OS in colorectal cancer patients treated with an anti-EGFR antibody." (PMID 35387120, 2022). "Acquired resistance to cetuximab in colorectal cancers is partially mediated by the acquisition of mutations located in the cetuximab epitope in the epidermal growth factor receptor (EGFR) ectodomain and hinders the clinical application of cetuximab." (PMID 35907884, 2022). "In colorectal cancer patients, 54.1% of all samples harbored a mutation known to confer anti-EGFR antibody resistance." (PMID 35486650, 2022). "In this work, we used WES based on cfDNA liquid biopsy for 55 lung and colorectal cancer patients to identify novel somatic variants associated with drug resistance after treatment including cytotoxic chemotherapy or EGFR targeted therapy." (PMID 35402275, 2022). "Here, we showed that Ephexin1, EphA2, and EGFR are each expressed at higher levels in lung and colorectal cancer patient tissues, and binding of EGFR to EphA2 was associated with both increased tumor grade and metastatic cases in both cancer types." (PMID 35668076, 2022). "Heterogeneity and adaptive alterations promote resistance to anti-EGFR targeted therapy and are strongly associated with the clinical outcome of colorectal cancer." (PMID 34663410, 2021).
colorectal cancer (continued). "These mutational profiles have prompted the need to evaluate triple combination therapies: currently, triple therapy with dabrafenib+trametinib+panitumumab (anti-EGFR) is being evaluated in colorectal cancer with EGFR mutation." (PMID 34804975, 2021). "Epidermal growth factor receptor (EGFR) is estimated to be overexpressed in 60~80% of colorectal cancer (CRC), which is associated with a poor prognosis." (PMID 33499047, 2021). "KRAS mutations were previously thought to be mutually exclusive with EGFR mutations and are a well-defined resistance mechanism to EGFR-mAbs in colorectal cancer." (PMID 34069119, 2021). "Due to this, downstream signaling in G13D-mutated cells is extremely RTK-dependent, possibly explaining why KRASG13D-mutated colorectal cancers are sensitive to EGFR-TKIs while other KRAS-mutated colorectal tumors are refractory to EGFR-TKI treatment." (PMID 33924994, 2021). "Treatment of colorectal cancer cells with the HDAC inhibitors Trichostatin A (TSA) or suberoylanilide hydroxamic acid (SAHA) was associated with reduced EGFR protein levels, for which HDACs 1, 2, and 3 were proposed to be responsible." (PMID 33976119, 2021). "The definition of R1 is largely concordant to the corresponding level-of-evidence (LOE) in OncoKB (e.g., KRAS exons 2–4 mutations for anti-EGFR antibodies in advanced colorectal cancers)." (PMID 34162978, 2021). "In conclusion, our results indicated that, c-Met/EGFR are important biomarker signatures of cancer-associated fibroblasts and tumor immune infiltration, and are of clinical relevance in colorectal cancer." (PMID 34512327, 2021). "Several studies offer insight on the behavior of PPIs in human diseases, in particularly oncogenic mutations of the epidermal growth factor receptor (EGFR) in colorectal cancer (CRC)." (PMID 33498632, 2021). "The insulin/IGF system was implicated in the development of drug resistance to epidermal growth factor receptor‐targeted agents and chemotherapeutic drugs in colorectal cancer." (PMID 34528373, 2021). "The BEACON trial showed that combination therapy with encorafenib (BRAF inhibitor) and cetuximab (EGFR inhibitor) was associated with prolonged overall survival compared with standard chemotherapy in patients with metastatic BRAF variant colorectal cancer." (PMID 33433598, 2021). "Since NF1 is frequently co-mutated in KRAS G13-mutated colorectal cancer, these tumor cells can respond to EGFR inhibitors in an NF1-dependent manner." (PMID 34680229, 2021). "The mutations of the EGFR gene are uncommon in colorectal carcinomas, enabling the use of the wild-type clone DAK-H1-WT for the research of the receptor." (PMID 34133521, 2021). "Colorectal cancer (CRC) is associated with resistance to anti-epidermal growth factor receptor (EGFR) antibodies (both acquired and intrinsic), owing to the amplification or mutation of the KRAS oncogene." (PMID 32703218, 2020). "Targeted therapy is a good method for the management of colorectal cancer through the use of “epidermal growth factor receptor inhibitors” (EGFR), such as CTX, which is linked to oral squamous cell carcinoma patient survival." (PMID 32170176, 2020). "For example, the loss of miR-7 in colorectal cancer promotes EGFR expression, the core of classic proliferative EGFR signaling pathway." (PMID 32799866, 2020). "RAS mutational status is used as a biomarker in colorectal cancer (CRC) to predict Epidermal Growth Factor Receptor (EGFR)-antibody response." (PMID 35582611, 2020). "In the present study, we examined the anti-tumor activities of a novel anti-EGFR monoclonal antibody, EMab-17 (mouse IgG2a, kappa), in colorectal cancer (CRC) cells with the KRAS p.G13D mutation." (PMID 32839411, 2020). "EGFR promoter hypermethylation in colorectal cancer has been found associated with patient resistance to anti-EGFR therapies." (PMID 32194414, 2020).
colorectal cancer (continued). "EGFR inhibition by monoclonal antibodies or small molecule TKIs has been approved for the treatment of tumor entities like RAS wild-type colorectal cancers, HNSCC, and EGFR-mutated NSCLC." (PMID 32978523, 2020). "Anti-EGFR antibody therapy for unresectable colon cancer was found to be ineffective in cases with RAS (KRAS/NRAS) gene mutations (about 40% of colorectal cancers), and RAS genetic testing was established as a companion diagnostic tool." (PMID 33383632, 2020). "It is estimated that EGFR is overexpressed in 60–80% of colorectal cancers, and its high expression is associated with a poor prognosis in patients with colorectal cancer." (PMID 32461676, 2020). "Here, blood samples were obtained from 105 patients that contained different cancer driver gene mutations, such as NSCLC patients with an EGFR gene mutation and colorectal cancer patients with a BRAF mutation." (PMID 32180799, 2020). "Data also demonstrated that there is a difference in EGFR protein expression between left- and right-sided colorectal cancers that is independent from the RAS mutation statuses." (PMID 32155907, 2020). "To evaluate the effect of miR-31-3p, miR-143 and miR-145 on the c-MYC expression in colorectal cancer, we deregulated these miRs in two anti-EGFR resistant cell lines: KRAS mutated (p.G13D) HCT116 and KRAS mutated (p.G12V) SW480 cell line." (PMID 32164324, 2020). "Mutations in the EGFR signaling pathway play an important role in the development of colorectal cancer (CRC)." (PMID 33680376, 2020). "While combination BRAF and MEK inhibition is proven to be of benefit in V600 mutated cholangiocarcinoma, additional EGFR inhibition is required in V600 mutated colorectal carcinoma." (PMID 32384640, 2020). "Mutations in the extracellular domain of EGFR were found in a few resistant colorectal cancer (CRC) patients after treatment with monoclonal antibody Cetuximab." (PMID 31508364, 2019). "Celecoxib is able to amplify EGFR activation in primary colorectal cancer-associated fibroblasts triggering sustained Erk1-2 and AKT signaling." (PMID 31816863, 2019). "Coexisting subclonal mutations in patients with fusion-present colorectal cancer implicate fusions as a previously unreported, novel mechanism of resistance to anti–epidermal growth factor receptor therapies in patients with metastatic colorectal cancer." (PMID 33015522, 2019). "For instance, in the ‘EGFR R451C-cetuximab-colorectal cancer’ example, the biomarker is associated to sensitivity to treatment at preclinical level but to resistance to treatment at clinical level." (PMID 31169290, 2019). "BRAF mutations occur in approximately 10% of colorectal cancers and are associated with resistance to anti-EGFR therapy." (PMID 31711486, 2019). "Mutations in either KRAS or BRAF drive colorectal cancers and predominate complementary pathways from EGFR that converge on FOXO3a." (PMID 30478887, 2019). "Hotspot testing for activating KRAS mutations is used in precision oncology to select colorectal cancer (CRC) patients who are eligible for anti-EGFR treatment." (PMID 31805664, 2019). "Further than RAS mutational status and EGFR activation, biological reasons behind the differences between left- and right-sided colorectal cancers are laid aside." (PMID 31344798, 2019). "Although a previous case report identified an HRAS G13D mutation in the resistance to anti-EGFR monoclonal antibodies in colorectal cancer, this is the first report of an HRAS-activating mutation conferring acquired resistance to AZD9291 in NSCLC." (PMID 29641535, 2018). "Low tumor EGFR expression in patients with colorectal cancer is associated with low tumor metastasis risk and better survival." (PMID 30187356, 2018). "β-Galactoside α-2,6-sialyltransferase 1 (ST6Gal1) catalyzes EGFR sialylation that is associated with gefitinib resistance in colorectal cancers, and this was also investigated." (PMID 30187356, 2018).
colorectal cancer (continued). "The only tests thus far approved by the FDA in the USA and China include the DNA methylation-based test of SEPT9 for the detection of colorectal cancer and the qPCR-based test for mutated EGFR in NSCLC." (PMID 30364656, 2018). "In the case of colorectal cancer, both type and location of KRAS mutations are known to predict response to EGFR inhibition in colorectal cancer." (PMID 30234014, 2018). "The upregulation of EGFR has been reported in colorectal cancer and is associated with poor prognosis and resistance to radiation therapy." (PMID 29777377, 2018). "EGFR mutations, gene amplifications, and overexpression are central features in a variety of human malignancies, including colorectal cancer, and biologic EGFR inhibitors such as cetuximab and panitumumab are commonly used for their anti-oncogenic activity." (PMID 29904166, 2018). "EGFR overexpression is associated with the development of several tumour malignancies, such as non-small cell lung cancer, ovarian cancer, colorectal cancer and head and neck cancer." (PMID 29552307, 2018). "Here we present the first GWAS to identify SNPs associated with EGFR inhibitor-induced skin toxicity using data of the multicenter randomized phase III CAIRO2 trial of the Dutch Colorectal Cancer Group (DCCG)." (PMID 30557370, 2018). "Until recently, indications for standard-of-care molecular testing in colorectal carcinomas included testing for KRAS mutational status as a predictor of response to anti–EGFR agents." (PMID 29755687, 2018). "To study the antitumor effects of the EGFR-targeted 4-1BB-agonistic trimerbody in immune competent mice, we used murine CT26 colorectal carcinoma (H-2d) cells infected with retrovirus encoding human EGFR (CT26hEGFR)." (PMID 30442944, 2018). "Expression of TGFα, EGF, and EGFR worsens prognosis and increases the metastatic potential of breast, renal, and colorectal cancers, all known to be obesity-associated malignancies." (PMID 27525640, 2017). "The importance of mutation identification for advanced colorectal cancer treatment with anti-epidermal growth factor receptor agents is well established." (PMID 28945877, 2017). "Subsequently, many mutation analyses of patient specimens have demonstrated EGFR gene amplification in various human tumors, including lung, head and neck, esophageal, and colorectal cancers." (PMID 29140271, 2017). "In colorectal cancer, EGFR antibody-resistant subclones with pre-existing KRAS mutations emerged in 38% of patients following 5–6 months of treatment with panitumumab." (PMID 28716075, 2017). "This is of special interest because KRAS amplifications in colorectal cancers were shown to be associated with resistance to EGFR inhibitors, including cetuximab." (PMID 29237412, 2017). "In conclusion, EZH2 expression was associated with survival in patients with colorectal cancer who were treated with anti-EGFR therapeutics." (PMID 28147317, 2017). "Currently, the BEACON phase III clinical trial (NCT02928224) is also evaluating the role of binimetinib in combination with a BRAF and EGFR inhibitor in BRAF mutated colorectal cancer patients." (PMID 29108355, 2017). "Activating KRAS mutations drive colorectal cancer tumorigenesis and influence response to anti‐EGFR‐targeted therapy." (PMID 28173629, 2017). "KRAS mutations drive resistance to targeted therapies, including EGFR inhibitors in colorectal cancer (CRC)." (PMID 28593995, 2017). "It was reported to be associated with primary or acquired resistance to EGFR blockade in colorectal cancers using circulating tumor DNA (ctDNA)." (PMID 27906677, 2017). "Colorectal cancer patients with the BRAF mutation in their tumours show resistance to the Epidermal growth factor receptor (EGFR) inhibitor Cetuximab and their response to the BRAF inhibitor Vemurafenib is limited." (PMID 29479053, 2017).